CCL2 (C-C motif chemokine ligand 2)
Diseases named in the same sentence as CCL2 in open-access papers (continued):
Sharing a sentence is not in itself a finding about the gene and the disease.
colorectal cancer (106 papers, 2011 to 2026). A primary or metastatic malignant neoplasm that affects the colon or rectum. "TCF4 enhances liver metastasis in colorectal cancer by regulating tumor-associated macrophages through CCL2/CCR2 signaling." (PMID 39100676, 2024). "In human colorectal cancer, the expression of CCL2 increases with cancer progression, and CCL2 deficiency has been associated with reduced infiltration of intratumoral MDSCs and smaller tumor sizes in spontaneous mouse models of colon cancer." (PMID 38720342, 2024). "For example, CCL2-mediated inflammation is associated with M2 polarized macrophages and tumorigenesis in colorectal cancer." (PMID 37108548, 2023). "High expression of CCL2 is associated with poor overall survival (OS) in colorectal cancer patients." (PMID 34464477, 2021). "Deletion of CCL2 blocked progression from dysplasia to adenocarcinoma and reduced the number of colonic MDSCs in a spontaneous mouse model of colitis-associated colorectal cancer." (PMID 33297571, 2020). "Recently, a CEACAM1-associated decrease of STAT3 activity and CCL2 secretion was found in colorectal carcinoma, thus regulating inflammatory signalling networks and decreasing metastatic burden." (PMID 30050594, 2018). "CCL2 was further implicated as a prognostic marker and an independent predictor of liver metastasis in colorectal cancer patients." (PMID 26885690, 2016). "This group of genes, represented by CCL2, have been reported to have the ability to recruit the tumor associated macrophage and to promote the progression of multiple cancers, including colorectal cancer." (PMID 26515597, 2015). "However, there are also reports that increased expression of CCL2 in tumor tissue is associated with better prognosis: These studies include patients with gastric cancer, colorectal cancer, liver cancer, and non-small cell lung cancer." (PMID 31823764, 2019). "A prior study reported that a STAT3-binding site present in the CCL2 promoter mediates CCL2 transcription in human colorectal cancer cells (blue highlight)." (PMID 40794443, 2025). "In colorectal cancer, Ccl2 promotes immunosuppression of T cells by regulating the priming of myeloid-derived suppressor cells." (PMID 39566333, 2025). "The promotion of colorectal cancer by Chemokine (CCL2) occurs through the enhancement of polymorphonuclear (PMN)-MDSC immunosuppressive features via the STAT3 pathway." (PMID 39100676, 2024). "Apart from its role as a chemoattractant, CCL2 facilitates the immunosuppression of T cells by regulating the suppressive functions of MDSCs via STAT3 in colorectal cancer and is expressed not only by cancer cells but also by TAMs and MDSCs." (PMID 38448555, 2024). "CCL2 was also reported require for colorectal cancer progression, which was secreted by Wnt5a+ TAMs." (PMID 38576043, 2024). "The study was designed to assay the efficacy of cenicriviroc (CVC) on the progression of mouse colorectal cancer by downregulation of CCR2_CCL2." (PMID 37325423, 2023). "The downregulation of CCL2 in MTA1-overexpressing colorectal cancer impaired the recruitment of monocytes and finally formed macrophages with a relatively decreased tumor microenvironment." (PMID 35350571, 2022). "We indicated that the serum concentration for CCL2 was statistically higher in the group of colorectal cancer patients when compared to healthy controls (p = 0.02)." (PMID 35407400, 2022). "In colorectal cancer, it is closely related to the number of tumors in the colon of mice and the level of CCL2 increases in patients with CRC." (PMID 36499169, 2022). "Wei et.al reported that the production of CCL2 promoted macrophage recruitment and subsequently colorectal cancer metastasis." (PMID 36230833, 2022). "The results indicated that DHZCP inhibits colorectal cancer liver metastasis, likely associated with blocking CCL2/CCR2 activation in the liver and suppressing the CCL2-mediated M2-skewing paradigm." (PMID 36105201, 2022).
colorectal cancer (continued). "This study further examines the role of the CCL2/MCP-1 axis in colorectal cancer via antibody mediated blockade of CCL2 combined with 5-FU chemotherapy in Balb/c mice with subcutaneous CT26 colon carcinoma allografts." (PMID 35461243, 2022). "In colorectal cancer, CCL2 was found to be strongly correlated with endothelial–mesenchymal transition, and inhibition of CCL2 significantly reduced macrophage infiltration and tumor metastasis mediated by circulating cancer cells." (PMID 34386431, 2021). "CAFs with high FAP expression recruit myeloid cells by upregulating CCL2 secretion to promote immunosuppression in the colorectal cancer tumor immune microenvironment." (PMID 34305902, 2021). "CCL2 promoted the progression of colorectal cancer and enhanced the polymorphonuclear MDSC population and function." (PMID 34464477, 2021). "Increased expression of CCL2 is an indicator of the progression of human colorectal cancer while inhibiting CCL2 was reported to reduce the recruitment of MDSCs in colorectal cancer model." (PMID 34336860, 2021). "As a result of examining the expression level of CCL2 from 245 colorectal cancer samples, the high expression level of CCL2 in the primary lesion was a significant marker for predicting liver metastasis." (PMID 33297571, 2020). "Correlation analysis of Twist1 and CCL2 expression in cohort (n=83) colorectal cancer (CRC) tissues." (PMID 33330033, 2020). "Colorectal cancer development is associated with the reduction of OXTR signaling since OXT can suppress FAPα and CCL-2 expressions and their associated CAC migration via OXTR." (PMID 31920487, 2019). "It was recently reported that CCL2 influences the expression of PD‐L1 in polymorphonuclear myeloid‐derived suppressor cells (PMN‐MDSCs) and that CCL2 promotes PMN‐MDSC‐mediated suppression of T cells in colorectal cancer." (PMID 27666332, 2016). "Colorectal cancer liver metastases are characterized by the infiltration of bone marrow-derived CD11b/Gr-1mid cells, in response to CCL2 secreted by CRC cells." (PMID 25882816, 2015). "Our study also showed that our colorectal cancer patients explant tissue secreted high levels of CCL2, CXCL1 and CXCL5, compared to VEGF." (PMID 22125641, 2011). "Interestingly, GCDCA has been shown to trigger the expression of inflammatory chemoattractant IL-8 and CCL2 in hepatocytes, and it has been positively correlated with colorectal cancer development and progression." (PMID 40476597, 2025). "M‐MDSCs play a crucial role in reactivating dormant colorectal cancer cells to potential metastatic cells by secreting CCL2 that binds to the receptor CCR2 on these dormant cells and activates the JAK‐STAT3 signaling pathway that promotes the transition from dormant to highly metastatic cells." (PMID 38703051, 2024). "TAMs have also been shown to promote invasion, migration, and metastasis in colorectal cancer via regulation of the JAK2/STAT3/miR‐506‐3p/FoxQ1 axis resulting in the production of CCL2 which in turn promotes the recruitment of more TAMs in a positive feedback loop." (PMID 38703051, 2024). "miR-206 mimic could restrain the CCL2 mRNA and protein, in addition, knockdown of HOTAIR significantly augmented mRNA and protein level of CCL2 in colorectal cancer cells." (PMID 32489462, 2020). "When the preoperative serum CCL2 concentration of 45 colorectal cancer patients was measured, the 5-year survival rate was significantly better in the group with low preoperative CCL2 level than in the group with high preoperative CCL2 level." (PMID 33297571, 2020). "Collectively, these results suggested that PIPKIγ may activate the PI3K-Akt-STAT3 signaling pathway, which can further increase CCL2 levels in colorectal cancer." (PMID 31781676, 2019). "Likewise, binding or either CCL8 or CCL2 to CCR2 on colorectal cancer cells can provoke a similar increase in migration and invasion." (PMID 26885690, 2016).
colorectal cancer (continued). "Moreover, it has been shown that CCL2 expression by colorectal cancer cells can recruit Gr-1+ cells, which are important for the establishment and growth of colorectal liver metastases." (PMID 25882816, 2015). "Hence, theoretically, targeting the CCL2(MCP1)/CCR2/MDSC pathway could potentially serve as an immune target for refractory colorectal cancer (CRC)." (PMID 39456702, 2024). "Similarly, CCL2 promotes the recruitment of immunosuppressive tumour-associated macrophages, promotes CT26 tumour growth and associates with poor outcomes in metastatic human colorectal cancer." (PMID 35226704, 2022). "In colorectal cancer, the lncRNA, LINC00543, blocks maturation of miR-506-3p, resulting in elevated FOXQ1 and subsequently CCL2, which recruits macrophages and skews macrophages toward the M2 phenotype." (PMID 41154428, 2025). "In colorectal cancer, for example, lncRNA HOTAIR functions as a sponge for miR-206 and frees CCL2 mRNA from being impacted by miR-206." (PMID 41154428, 2025). "For example, TAMs have been shown to regulate the IL-6/JAK2/STAT3/miR-506-3p/FoxQ1 axis, which enhances colorectal cancer (CRC) motility and invasion through the induction of EMT and upregulation of CCL2, promoting macrophage recruitment." (PMID 40083697, 2025). "In colorectal cancer (CRC), expression of chemokine (C-C motif) ligand 2 (CCL2) drives migration of PMN-MDSCs into the tumor, suppressing immune responses and enhancing tumor progression." (PMID 38474232, 2024). "Chemokines, including CXCL10, CXCL12, CX3CL1, CCL2, CCL5, CCL18, and CCL20, induce chemotaxis to promote cell migration and invasion in ovarian, lung, breast, and colorectal cancers." (PMID 38438872, 2024). "Targeting the MDSC-related CCL2(MCP1)–CCR2 pathway holds promise as a therapeutic approach, particularly in refractory colorectal cancer." (PMID 39456702, 2024). "Another study showed that colorectal cancer cells promote the polarization of macrophages to the M2 phenotype characterised by surface marker CD163, mediated by CCL2 and ICAM1." (PMID 37108548, 2023). "With the progression of tumor, chemokines such as CCL2, CCL7, CCL8, and CCL15 in the microenvironment of colorectal cancer gradually increase, recruiting monocytes and Th1 cells to the tumor region." (PMID 37063892, 2023). "During bevacizumab treatment of colorectal cancer patients with positive expression of ETV5, the secretion of CCL2 induced by ETV5 resulted in persistent angiogenesis, indicating that CCL2 plays a critical role in bevacizumab resistance." (PMID 36077785, 2022). "In Caco-2, a cell line of human colorectal cancer, C. botulinum type A 62A MVs induced the highest expression levels of IL6, IL8, and CCL2, while C. scindens VPI12708 MVs induced the lowest." (PMID 35185840, 2022). "That is why the aim of our study was an attempt to clarify and to assess the usefulness of selected CC-chemokine measurement (CCL2, CCL4 and CCL15) in patients with colorectal cancer compared to the healthy volunteer group." (PMID 35407400, 2022). "A previous study showed that NT5DC2 deletion obviously reduced the tumor-associated macrophage (TAM) recruitments through suppressing CCL2/CCR2 and AKT/NF-κB signaling pathways in colorectal cancer." (PMID 35047040, 2022). "We noticed that the CCL2 and CCL4 areas under the ROC curve (0.634; 0.630, respectively) in the entire group of colorectal cancer were highest from all newly tested parameters, but lower than AUC for CEA and CRP." (PMID 35407400, 2022). "In colorectal cancer, TAMs secrete CCL2 via Wnt5a/CaMKII/ERK/CCL2 axis, and those CCL2 molecules act on cancer cells and drive tumor progression." (PMID 36268282, 2022). "In a mouse model of transplantable colorectal carcinoma (CRC), it was found that fibroblasts expressing high levels of FAPα recruited myeloid cells via CCL2, which resulted in resistance to anti-PD-1 immune checkpoint therapy that was eliminated by targeting the FAPα." (PMID 36555218, 2022).
colorectal cancer (continued). "For example, Wnt5a+ TAMs enhance C-C motif chemokine ligand 2 (CCL2) secretion through the calcium/calmodulin-dependent protein kinase II (CaMKII)-ERK pathway, which contributes to colorectal cancer growth, metastasis, and recruit infiltrating macrophages." (PMID 33406733, 2021). "Correlation analysis of FOXQ1 and Twist1, CCL2, or CD31 expression in cohort (n=83) colorectal cancer (CRC) tissues." (PMID 33330033, 2020). "We showed here higher serum levels of IL1B, IL6, CXCL8, TNFA, CCL2 and tumor levels of IL1B, IL6, CXCL8, TNFA in colorectal cancer, suggesting the involvement of these inflammatory factors in colorectal cancer." (PMID 31528237, 2019). "For instance, the two well-known SASP factors, CXCL8/IL-8 and CCL2/MCP-1, increase the migration of colorectal cancer cells." (PMID 27907906, 2016). "In the following sections, we highlight effects of CCL2/CCR2 signaling in several experimental studies on metastatic cancers, with a particular focus on prostate, breast and colorectal cancers." (PMID 26885690, 2016). "Levels of CCL2, CXCL1 and CXCL5 were consistently higher than those of VEGF (a current therapeutic target in colorectal cancer) in all patients examined." (PMID 22125641, 2011). "Similarly, in colorectal cancer, PDPN+ CAFs secrete CCL2 to establish a PDPN/CCL2/STAT3 autocrine feedback loop that maintains CAFs heterogeneity and, via paracrine signaling, activates STAT3 in ECs to drive angiogenesis." (PMID 41514658, 2025). "Finally, in colorectal cancer, Klotho suppresses the tumorigenic effects of senescent stromal cells by suppressing SASP factors and CCL2." (PMID 40004457, 2025). "CCL2 enhances the number and function of PMN-MDSCs, promoting colorectal cancer." (PMID 39100676, 2024). "In colorectal cancer (CRC), TAMs induce EMT program to enhance CRC migration, invasion, and CTC-mediated metastasis by regulating the JAK2/STAT3/miR-506-3p/FoxQ1 axis, which in turn leads to the production of CCL2 that promote macrophage recruitment." (PMID 36817086, 2023). "Indeed, the combination of anti-CCL2 and bevacizumab inhibited ETV5-positive colorectal cancer angiogenesis more efficiently than either of them alone." (PMID 36077785, 2022). "Correlation analysis of CCL2 and CD68 expression in cohort (n=83) colorectal cancer (CRC) tissues." (PMID 33330033, 2020). "In colorectal cancer cells, β-catenin regulates the activity of the NF-κB promoter, whereas inhibition of GSK-3β by lithium or siRNA potentiated TNF-induced expression of IL-6 and CCL2 in human microvascular endothelial cells." (PMID 33171974, 2020). "Interestingly, FAP+CAF‐secreted CCL2 has previously been shown to activate myeloid‐derived suppressor cells (MDSC), resulting in tumour growth and proliferative suppression of T cells in colorectal cancer." (PMID 39743376, 2025). "Moreover, CHI3L1 exerts direct effects on SW480, a human colorectal cancer cell line, by activating the NF-κB and MAPK pathways, consequently upregulating the expression of pro-inflammatory cytokines/chemokines such as TNFα, IL-8, and CCL2 (C-C motif chemokine ligand 2)." (PMID 38667293, 2024).
influenza (106 papers, 2008 to 2025). An acute viral infection of the respiratory tract, occurring in isolated cases, in epidemics, or in pandemics; it is caused by serologically different strains of viruses (influenzaviruses) designated A, B, and C, has a 3-day incubation period, and usually lasts for 3 to 10 days. "Cytokine, chemokine, and interferon levels are altered during influenza infection in IL‐6 deficient mice, including increased TGFβ by day 6 post‐infection and increased TNFα, IFNα, and CCL2 by day 7 post‐infection." (PMID 40420617, 2025). "In the case of influenza, depletion of macrophages prior to infection leads to uncontrolled viral replication and a recent study has implicated the chemokine CCL2 (MCP-1) in alveolar regeneration following influenza infection." (PMID 21789257, 2011). "Previous studies show that the chemokine receptor CCR2 (the primary receptor for CCL-2) is crucial in severe influenza infection." (PMID 40626651, 2025). "The production of several chemokines involved in influenza severity, including CCL2/MCP-1, CCL3/MIP-1α, CCL4/MIP-1β, CCL5/RANTES, CXCL2/MIP-2, and CXCL10/IP-10 was also quantified." (PMID 40612502, 2025). "Conversely, toddlers produced more of the pro-inflammatory cytokines CCL2 and PAI1, both associated with more severe influenza infection." (PMID 41282111, 2025). "Conversely, toddlers exhibited elevated levels of CCL2 and PAI1, which are associated with increased severity of influenza infection and inflammation." (PMID 41282111, 2025). "We found increased expression of influenza M protein, Stat1, Oasl2, and CCL2 in influenza-infected mice when compared to PBS-treated controls." (PMID 38750107, 2024). "In response to influenza viral entry, epithelial cells induce proinflammatory cytokines and chemokines such as IL-1β, IL-6, TNFα, CCL2, CCL3, and CCL5, which recruit macrophages and neutrophils to the site of infection to help control the virus." (PMID 38112660, 2023). "Reduction in CCL-2 and trafficking of mononuclear cells to the infection site can efficiently ameliorate the lethal effects of influenza." (PMID 35606770, 2022). "Infection of mice with virulent strains of influenza leads to increased expression of IFNs and concomitant overexpression of CCL2, which induces excessive recruitment of inflammatory monocytes and immunopathology." (PMID 34691044, 2021). "It is known that type I IFN induced by influenza can inhibit the production of the chemokine CCL2, which is important for macrophage recruitment." (PMID 35049941, 2021). "In particular, we observed an upregulation of IL-8 and CCL2 expression following Flu Avert treatment, which agrees with other studies investigating mucosal chemokine responses to influenza vaccination." (PMID 34179166, 2021). "Influenza infection induces a variety of inflammatory cytokines and chemokines such as IL-6, IL-8, TNFα, CCL2, CCL5, CXCL10, and recruitment of neutrophils and macrophages to clear the virus." (PMID 31159430, 2019). "Influenza infection induced a variety of inflammatory cytokines such as IL-1β, IL-6, TNFα, IL-8, CCL2, CCL5, and CXCL10 from epithelial and immune cells." (PMID 30337919, 2018). "Although increased expression of CCL2 during influenza infection has been well-documented, the effects of the CCL2/CCR2 pathway on the pathogenesis of infection are controversial." (PMID 28421067, 2017). "CCL2 has also recently been proposed as a biomarker for prediction of symptomatic influenza infection in humans." (PMID 26393920, 2015). "During early influenza infection, airway epithelial cells produce CCL2 (MCP-1), which attracts CCR2+ monocytes into the lung tissue from the blood." (PMID 23304058, 2012). "Mice treated with anti-CCL2 mAb had reduced cellular infiltration, including macrophages and neutrophils, following influenza infection, further implicating the role of macrophages in the resolution phase of the infection." (PMID 21789257, 2011).